DLC1 (DLC1 Rho GTPase activating protein)
Description:
Functions as a GTPase-activating protein for the small GTPases RHOA, RHOB, RHOC and CDC42, terminating their downstream signaling. This induces morphological changes and detachment through cytoskeletal reorganization, playing a critical role in biological processes such as cell migration and proliferation. Also functions in vivo as an activator of the phospholipase PLCD1. Active DLC1 increases cell migration velocity but reduces directionality. Required for growth factor-induced epithelial cell migration; in resting cells, interacts with TNS3 while PTEN interacts with the p85 regulatory subunit of the PI3K kinase complex but growth factor stimulation induces phosphorylation of TNS3 and PTEN, causing them to change their binding preference so that PTEN interacts with DLC1 and TNS3 interacts with p85. The PTEN-DLC1 complex translocates to the posterior of migrating cells to activate RHOA while the TNS3-p85 complex translocates to the leading edge of migrating cells to promote RAC1 activation.
Synonyms: DLC-1; StARD12; ARHGAP7; HP; p122-RhoGAP
Tractability: Antibody: UniProt places it where antibodies can reach, with medium confidence. PROTAC: ubiquitination databases record sites on it.
Gene: Protein-coding gene on chromosome 8 (13,083,361 to 13,604,610, reverse strand). Ensembl gene ENSG00000164741.
Subcellular location: Cytoplasm; Cell junction, focal adhesion; Membrane
Subcellular location (Human Protein Atlas): Cytosol; Endoplasmic reticulum; Vesicles
Pathways (Reactome):
Signal Transduction: CDC42 GTPase cycle; RAC1 GTPase cycle; RHOA GTPase cycle; RHOB GTPase cycle; RHOC GTPase cycle; RHOQ GTPase cycle
Gene Ontology:
Molecular function: GTPase activator activity; protein binding; SH2 domain binding; lipid binding
Biological process: intracellular signal transduction; negative regulation of cell migration; negative regulation of cell population proliferation; negative regulation of focal adhesion assembly; negative regulation of Rho protein signal transduction; negative regulation of stress fiber assembly; positive regulation of execution phase of apoptosis; actin cytoskeleton organization; focal adhesion assembly; forebrain development; heart morphogenesis; hindbrain morphogenesis; neural tube closure; regulation of Rho protein signal transduction; regulation of small GTPase mediated signal transduction; signal transduction
Cellular component: caveola; cortical actin cytoskeleton; cytoplasm; cytosol; focal adhesion; nucleus; ruffle membrane; membrane raft; membrane
Genetic constraint (gnomAD): Loss-of-function variants: 54 observed, 142.92 expected, observed/expected ratio (o/e) 0.38, 90% interval 0.3 to 0.47. The synonymous counts are far from expectation, so gnomAD's model fits this gene poorly and the ratio says little. Missense variants: 2,536 observed, 2,007.5 expected, observed/expected ratio (o/e) 1.26, 90% interval 1.22 to 1.3. Synonymous variants: 986 observed, 771.83 expected, observed/expected ratio (o/e) 1.28, 90% interval 1.21 to 1.35.
Homologues: Orthologues: chimpanzee DLC1 (99% identical), macaque DLC1 (97% identical), dog DLC1 (91% identical), pig DLC1 (90% identical), rabbit DLC1 (89% identical), rat Dlc1 (85% identical), mouse Dlc1 (85% identical), guinea pig DLC1 (66% identical), tropical clawed frog dlc1 (63% identical), zebrafish dlc1 (44% identical), Caenorhabditis elegans gei-1 (22% identical). Paralogues in human: STARD13 (39% identical), STARD8 (31% identical).
Diseases named in the same sentence as DLC1 in open-access papers:
DLC1 is named in the same sentence as 108 diseases in open-access papers, as found by Europe PMC text mining. Sharing a sentence is not in itself a finding about the gene and the disease. The quoted sentences say what the papers report.
hepatocellular carcinoma (49 papers, 2008 to 2025). A malignant tumor that arises from hepatocytes. "Tumor suppressor gene DLC1, firstly isolated from human primary hepatocellular carcinoma, is located on chromosome 8p21-22 and encodes a Rho GTPase-activating protein." (PMID 28903430, 2017). "A gene that is located within this region is the Deleted in Liver Cancer 1 (DLC1), which was reported to be a tumor suppressor gene and has been shown to undergo copy number loss in several cancers, such as hepatocellular carcinoma and breast cancer." (PMID 24694993, 2014). "Deleted in liver cancer-1 gene (DLC-1) which is isolated from human hepatocellular carcinoma and encodes a Rho GTPase-activating protein, is frequently inactivated or down-regulated in liver and prostate carcinoma cells." (PMID 19715608, 2009). "Loss of DLC1 is considered an independent marker of hepatocellular carcinoma." (PMID 26217396, 2015). "In this study, we report that therapeutic knockdown of MKL1/2 abolishes tumour growth of DLC1-deficient hepatocellular carcinoma (HCC) xenografts by inducing oncogene-induced senescence." (PMID 23853104, 2013). "Similar to GMIP, DLC1—another family member—acts as a tumour suppressor in hepatocellular carcinoma by regulating Rho protein activity." (PMID 40275529, 2025). "Recently, scientists suggested that DLC-1 plays a critical role in tumorigenesis in several cancer models, such as gallbladder carcinoma, gastric cancer, and hepatocellular carcinoma." (PMID 38322013, 2023). "Accordingly, the function of DLC1 has been revealed, as reflected by the fact that elevating DLC1 attenuates the aggressive activities of hepatocellular carcinoma cells." (PMID 35414117, 2022). "Only 5 genes were obtained in the intersection of 5 databases, among which DLC1, also named Delete in liver cancer-1, was a metastasis suppressor in hepatocellular carcinoma." (PMID 35280693, 2022). "DLC-1 is a GTPase-activating protein that targets Rho, and as a tumor suppressor, DLC-1 is not only involved in hepatocarcinogenesis, but also inhibits the cancer progression and oncogenic autophagy of hepatocellular carcinoma." (PMID 34095224, 2021). "LUCAT1 can activate the metalloproteinase protein, regulating the expression of DLC1, and enhance the malignant phenotype of hepatoma cells." (PMID 34901153, 2021). "DLC1 is known to inhibit cancer progression and oncogenic autophagy in patients with hepatocellular carcinoma." (PMID 34790823, 2021). "For instance, DLC-1 expression is reduced 10-fold in lung adenocarcinoma, 3-fold in hepatocellular carcinoma, 4-fold in breast cancer, and 3-fold in colon cancer." (PMID 33142932, 2020). "Apart from its cytoplasmic role in regulating Rho signaling, DLC1 can be localized in the nucleus where it was shown to be less efficient in exerting tumor-suppressor activity in hepatocellular carcinoma." (PMID 32214200, 2020). "These copy number losses were 50% more common in female-derived tumours and affect genes such as DLC1, a known tumour suppressor gene in hepatocellular cancer that is thought to have a similar role in gallbladder cancer." (PMID 32859912, 2020). "Overexpression of DLC1 contributes to apoptosis by up-regulating level of Bax and activity of caspase-3 in hepatocellular carcinoma and cutaneous squamous cell carcinoma cell lines." (PMID 28903430, 2017). "Overexpression of DLC1 stimulates cell apoptosis by elevating caspase-3 activity and decreasing Bcl-2 level in hepatocellular carcinoma and cutaneous squamous cell carcinoma cells." (PMID 28903430, 2017). "Deleted in liver cancer-1 (DLC-1) was first cloned by using subtractive hybridization method in human hepatocellular carcinomas and later it was identified as a breast cancer metastasis suppressor in microarray comparisons between breast cancer cell lines." (PMID 26846339, 2016). "The DLC-1 (Deleted in liver cancer 1) gene was originally discovered as a potential tumor suppressor frequently deleted in hepatocellular carcinoma." (PMID 27366946, 2016).
hepatocellular carcinoma (continued). "Studies done on DLC1, a closely related gene, reported its function as a candidate tumor suppressor in hepatocellular carcinoma." (PMID 24627003, 2014). "DLC1, a tumor suppressor gene, is frequently silenced in various types ofhuman cancer.DLC1 was first identified in primary human hepatocellular carcinoma, withan inhibitory effect on the growth of breast and liver tumors." (PMID 23708087, 2013). "In a mouse model of hepatocellular cancer expression of DLC1 significantly suppresses dissemination of tumor cells, while restoration of DLC1 expression in a mouse breast cancer model resulted in a significant decrease in metastases." (PMID 23056464, 2012). "DLC1 was recently identified due to its deletion in primary hepatocellular carcinoma and was mapped to 8p21.3–22, which is a reported site of tumor suppressor genes." (PMID 22272086, 2011). "The deletion in liver cancer gene (DLC1) is a tumor suppressor gene that was first identified by its deletion in a primary hepatocellular carcinoma sample and subsequently found to be deleted or under-expressed in other cancers." (PMID 22272086, 2011). "As a tumor suppressor gene, DLC1 significantly inhibits cell proliferation, reduced the motility and invasiveness of hepatocellular carcinoma cells." (PMID 19715608, 2009). "Cell migration and invasion have been proven to be important roles of CTEN, involving several proteins and signaling pathways, including KRAS/BRAF, Src/ROCK/SNAIL, ILK, and FAK in colorectal and pancreatic cancer, and Rho/ROCK/MLC in hepatocellular carcinoma, via DLC-1." (PMID 36851390, 2023). "When tensin-2 complexes with DLC1 on the caveolae, it inhibits hepatoma cell growth." (PMID 36106167, 2022). "DLC-1 expression restoration in hepatoma cells could induce cell apoptosis, and inhibit tumour growth." (PMID 30069430, 2018). "For instance, the tumor suppressor DLC1 may interact with TNS2 and contribute to the growth-suppressive activity of DLC1 in hepatocellular carcinoma." (PMID 30419905, 2018). "There are similarities between obesogenic and oncogenic states, namely cellular proliferation and inflammation, and it is interesting to note, that in this study two of the genes with significant methylation, DLC1 and CRYL1, are associated with hepatocellular carcinoma." (PMID 28068899, 2017). "DLC1, a tumor suppressor gene, is firstly found in human primary hepatocellular carcinoma." (PMID 28903430, 2017). "DLC1 has been shown to be downregulated or absent in hepatocellular carcinoma (HCC) and is associated with tumorigenesis and development." (PMID 26095787, 2015). "DLC-1 (Deleted in liver cancer-1) was initially isolated from primary hepatocellular carcinoma." (PMID 26260454, 2015). "Recently, abnormal, low, or lack of DLC1 expression was found to be associated with the metastasis of breast and hepatocellular cancers, suggesting that DLC1 plays an important role not only in tumorigenesis but also in metastasis." (PMID 23988121, 2013). "To further investigate whether loss of the tumour suppressor DLC1 is required for the proliferation arrest upon MKL1/2 knockdown, we depleted MKL1 and 2 in 4 different hepatoma cell lines (HuH7, HLF, HepG2 and HuH6)." (PMID 23853104, 2013). "Recently, abnormal, low, or lack of DLC1 expression was also associated with the metastasis of breast and hepatocellular cancers, suggesting that DLC1 plays an important role not only in tumorigenesis but also in metastasis." (PMID 22272086, 2011). "DLC1 can inhibit the metastasis of hepatocellular carcinoma by dephosphorylation of FAK." (PMID 22272086, 2011).
hepatocellular carcinoma (continued). "Deleted in liver cancer 1 (DLC1) is a tumor suppressor gene located on chromosome 8p21.3-22 and has been shown to be frequently unexpressed in a wide range of human cancers, including hepatocellular carcinoma (HCC)." (PMID 19440389, 2009). "The initial characterisation of p122RhoGap was soon followed by the discovery that the Dlc1 gene was part of a common 600 Kb genomic deletion in primary human hepatocellular carcinomas (HCC)." (PMID 26977077, 2016). "Restore DLC-1 expression in hepatoma cells could induce cell apoptosis, and inhibit tumor growth." (PMID 24916440, 2014). "The reduced expression of Dlc1 mRNA has been correlated with the invasiveness of hepatocellular carcinoma (HCC)." (PMID 22792269, 2012). "Deleted in Liver Cancer 1 (DLC1) was first cloned by subtractive hybridization as a gene fragment that was frequently deleted in human hepatocellular carcinoma (HCC)." (PMID 21966542, 2011). "Deleted in liver cancer 1 (DLC1) is a Rho GTPase-activating protein (RhoGAP) frequently deleted and underexpressed in hepatocellular carcinoma (HCC) as well as in other cancers." (PMID 19440389, 2009). "In the present study, we aimed to investigate the effects of DLC1 on Rho/ROCK signaling pathway in hepatocellular carcinoma (HCC)." (PMID 18648664, 2008). "DLC1 is a GAP for RhoA, which is often deleted in hepatocellular carcinoma and inactive in various types of human cancers including colon cancer." (PMID 34958986, 2022). "For example, phosphorylation of DLC1 by PKA enhances RhoGAP activity of DLC1, and further suppresses proliferation and metastasis both in hepatoma cells and in nude mice by mouse hepatoma cell subcutaneous injection." (PMID 28903430, 2017). "DLC1 has been reported to dephosphorylate FAK and inhibit the proliferation and migration of hepatocellular carcinoma cell lines." (PMID 28881822, 2017). "This implicates a ROCK-mediated pathway of DLC1 in suppressing metastasis of HCC cells and enriches our understanding in the molecular mechanisms involved in the progression of hepatocellular carcinoma." (PMID 18648664, 2008). "Research has shown that DLC1, as a gene from the same family as GMIP, acts as a tumour suppressor in hepatocellular carcinoma and provides evidence supporting the hypothesis that DLC1 inhibits cancer cell growth by negatively regulating Rho protein activity." (PMID 40275529, 2025). "Previous studies have suggested cten, a tensin family member, may function as a tumor suppressor, through the interaction with DLC-1 that has been found to be absent or suppressed in many cancers such as hepatocellular carcinoma (HCC)." (PMID 21765928, 2011). "Conversely, reduced DLC1 expression predominated in lung squamous cell carcinoma (LSC), lung adenocarcinoma (LAD), breast cancer, and hepatocellular carcinoma (HCC), but not in colorectal cancer." (PMID 27174913, 2016).
breast carcinoma (48 papers, 2008 to 2025). "Others have shown that DLC1 loss is sufficient to promote a more migratory behavior of breast cancer cells." (PMID 20799942, 2010). "DLC1-KIBRA interaction which is essential for ER transactivation in breast cancer cells explains the resistance to endocrine therapy through loss of ER functions in ER positive but KIBRA-low breast cancers." (PMID 29793439, 2018). "Overexpression of DLC1 in the metastatic M4A4 breast cancer cell line inhibited pulmonary metastasis formation in an orthotopic mouse model, while primary tumor growth remained unaffected." (PMID 40354489, 2025). "They characterized the upregulation of DLC1 prominently suppressing theCAV-1 in breast cancer cells." (PMID 38820323, 2024). "The DLC-1 gene acts as a tumor suppressor gene in a number of common cancers, including prostate, lung, colorectal, and breast cancer." (PMID 38392212, 2024). "A study using a breast cancer cell line suggests that TNS3 silencing activates the Rho-GAP function of DLC1 through releasing an autoinhibitory effect, and thereby elevating the level of RhoA-GTP." (PMID 37668682, 2023). "In breast cancer (BC), DLC1 was found to be deleted in 33% of samples while promoter hypermethylation or missense mutations did not frequently occur." (PMID 35322810, 2022). "Here we show that in breast cancer cells, dysregulation of DLC1 expression occurs at the protein level through rapid degradation via the ubiquitin–proteasome system." (PMID 35322810, 2022). "DLC1 SAM domain-binding peptides have been reported to inhibit breast cancer growth and migration through inactivation of RhoA and ROCK1 can promote migration and invasion of non small cell lung cancer by activating PTEN/PI3K/FAK pathway." (PMID 32546278, 2020). "EZH2 was highly expressed in breast cancer tissues (t = 9.236, P = 0.000), while DLC1 was expressed at low levels in breast cancer tissues (t = −3.238, P = 0.002)." (PMID 32725802, 2020). "A previous report demonstrated that DLC1 inhibited TGF-β-induced expression of parathyroid hormone-like hormone through suppression of Rho-ROCK signaling to prevent breast cancer bone metastasis." (PMID 32214200, 2020). "Our research demonstrated that EZH2 was up‐regulated in breast cancer (BC) tissues and cells, whereas DLC1 was down‐regulated, and the expression of EZH2 and DLC1 was negatively correlated in BC." (PMID 32725802, 2020). "Their findings indicated that DLC1-KIBRA interaction is essential for ER transactivation in breast cancer cells." (PMID 29793439, 2018). "The idea that aberrant RhoA activation drives breast cancer metastasis fits with the findings of others indicating that reduced expression of the RhoA subfamily-specific GAP DLC-1 is predictive of metastatic spread to the bone in all breast cancer subtypes." (PMID 29769144, 2018). "For example, the RhoGAP DLC-1 is deleted or epigenetically silenced in many breast cancer subtypes, driving aberrant RhoA activation and metastatic spread to the bones." (PMID 29769144, 2018). "PKD also directly phosphorylates DLC1 and negatively regulates DLC1 activity in breast cancer cells." (PMID 28903430, 2017). "DLC1 phosphorylation by PKC and PKD is required for interaction with 14-3-3 protein and inhibits the RhoGAP activity of DLC1 in breast cancer cells." (PMID 28903430, 2017). "Analysis of breast cancer subtypes indicated that the expression of DLC1, DLC2, and DLC3 was significantly lower in triple-negative breast cancer (TNBC) than in the other subtypes." (PMID 27174913, 2016). "Bend3 endothelial and Neu oncogene induced mammary tumour cell lines were used as constitutively high Dlc1 expressing cell types." (PMID 26977077, 2016). "Deleted in Liver Cancer 1 (Dlc1) is a tumor suppressor gene, which maps to human chromosome 8p21-22 and is found frequently deleted in many cancers including breast cancer." (PMID 26353792, 2015).